PGK1 (phosphoglycerate kinase 1)
Diseases named in the same sentence as PGK1 in open-access papers (continued):
Sharing a sentence is not in itself a finding about the gene and the disease.
cancer (continued). "Through physical interaction with its homologous partner SPIB, SPI1 is activated to promote aerobic glycolysis of cancer cells via upregulating HK2 or phosphoglycerate kinase 1 (PGK1), which in turn induces N2 polarization of neutrophils via glycolytic metabolite lactate." (PMID 34841706, 2021). "Furthermore, PGK1 is relative with cancer cell metastatic ability because HIF-1α/PGK1 mediated epithelial-mesenchymal transition (EMT) process." (PMID 34291087, 2021). "At the same time, PGK1 promotes glucose uptake and lactate production in cancer cells." (PMID 33344462, 2020). "Phosphoglycerate kinase 1 promotes cancer cell proliferation, invasion and metastasis." (PMID 33344462, 2020). "In addition, PGK1 glycosylation was observed across different human cancer cell lines, although with various levels." (PMID 31911580, 2020). "In addition, the function of PGK1 in cancer progression is complicated and has been reported in recent years." (PMID 32489020, 2020). "Besides, it has been well established that PGK1 can function as a protein kinase and regulate the glycolysis metabolism of cancer cells during carcinogenesis." (PMID 32565733, 2020). "Intriguingly, these 11 probes were all located in the PGK1 promoter regions, ranging from 500 nt upstream of the transcription start site (TSS500) to the 5′-untranslated region (5′-UTR), indicating that the PGK1 promoter regions were hypomethylated in these five types of cancer." (PMID 31578148, 2019). "Overexpression of PGK1 in PM does not appear to be just an epiphenomenon associated with increased glucose metabolism in cancer." (PMID 31198853, 2019). "To investigate whether NFAT5 performs a pro-cancer function via PGK1, we over-expressed PGK1 in AsPC-1 and BxPC-3 with knockdown of NFAT5." (PMID 31827081, 2019). "In the present study, we investigated the clinical relevance of PGK1 in human cancers and found that elevated PGK1 mRNA level and PGK1 protein kinase activity were associated with advanced TNM stages and poor prognosis in multiple human cancers." (PMID 31578148, 2019). "Therefore, in the present study, we analyzed the DNA methylation data for 14 cancer types from TCGA datasets and identified hypomethylation of the PGK1 promoter (cg13203541) as an independent prognostic biomarker in BRCA patients." (PMID 31578148, 2019). "However, the clinical significance of PGK1 expression and function in cancer progression is unclear." (PMID 31578148, 2019). "Additionally, HPRT and PGK1 show additional promise as possible biomarkers for cancer grade as the levels of the proteins elevated in a stepwise manner with higher cancer grade." (PMID 30679932, 2019). "Indeed, despite all the observations that report PGK1 overexpression in many cancer types, the role of this enzyme in tumorigenesis is yet unclear." (PMID 29995887, 2018). "A less efficient PGK1 in cancer cells may point to its moonlighting functions to satisfy cancer cell proliferation and survival requirements." (PMID 29995887, 2018). "K220 acetylation inhibits PGK1 activity/function and reduces the 3-PG and serine levels, implying that modulation of PGK1 activity/function by acetylation may serve as a promising anti-cancer strategy through regulating serine metabolism." (PMID 26356530, 2015). "Taken together, cancer-associated up-regulation of the reference genes used in the present study was (i) definitely present (PGK1), (ii) vaguely present (GAPDH) or (ii) absent (ACTB)." (PMID 26468005, 2015). "Since PGK1 promotes metastasis in some cancer types, blocking its extracellular release could enhance cancer dissemination." (PMID 24346158, 2014). "While the exact mechanism through which lncRNA-MVIH inhibits PGK1 secretion remains elusive, a dynamic influence of lncRNAs on the extracellular milieu is consistent with the idea that they represent master regulators of cancer metastasis." (PMID 24346158, 2014). "In several types of cancer, PGK1 has been shown to be up-regulated." (PMID 19221597, 2009).
cancer (continued). "Furthermore, PGK1, a key metabolic regulator, has been widely studied in various cancers." (PMID 40529105, 2025). "Furthermore, the role of PGK1 in cancer cell metabolism is significantly compelling." (PMID 40771921, 2025). "We performed differential expression testing to found that cluster C3 over-expresses ENO1, BNIP3, PGK1 and LDHA, 4 genes associated with hypoxia (absolute log fold change above 0.5 and Wilcoxon test p-values below 0.01), that have been previously associated with cancer progression." (PMID 37917660, 2023). "Our results also showed that knockdown of circROBO1 could decrease the PGK1 expression, which afterwards significantly inhibited the proliferation of cancer cells, and decreased the glucose consumption and lactate production in cancer cells." (PMID 37670963, 2023). "Additionally, PGK1 plays an important role in anti-cancer treatments." (PMID 38136210, 2023). "It is very interesting that phosphoglycerate kinase 1, in addition to being presented as curcumin’s binding partner, turned to be listed as downregulated in all the proteomic studies we could find that were related to cancer and curcumin." (PMID 37376060, 2023). "Nevertheless, the essential role of PGK1 in cancer development remains unclear." (PMID 34091600, 2021). "Thus, regulating the PTMs of PGK-1 to block glycolysis and proliferation in tumors may provide novel methods for cancer therapy." (PMID 33256814, 2020). "Thus, PGK1 inhibition with small interfering RNAs (siRNAs) or other approaches may provide a new strategy for cancer treatment." (PMID 33344462, 2020). "Thus, we underscore that PGK1 protein kinase activity is a potential target for cancer treatment." (PMID 31578148, 2019). "Thus, targeting PGK1 can be an attractive therapeutic approach for cancer treatment." (PMID 30367676, 2018). "Indeed, it has been demonstrated that, in addition to its role as a glycolytic enzyme, PGK1 may act as a promoter of cancer progression and induce chemoresistance for some drugs." (PMID 28686225, 2017). "In general, the associations between Carbon Metabolism and Pathway in Cancer genes become weaken in HCC, whereas the associations between a number of genes are enhanced, especially those in the 22 up-regulated carbon metabolism genes group (such as HK1, PGK1, ENO1, PGLS, RPE)." (PMID 27363021, 2016). "Although increased angiogenesis is a hallmark of cancer, the early pre-leukemic changes are characterized by reduced number of EC, reduced VEGFR1, and -2 signaling, and increased expression of the HIF-1α target genes Pgk1- and Eno1 by CD31+ CD45- Ter119- cells." (PMID 26308666, 2015). "Elevated expression of PGK-1, which is one of the enzymes in the glycolytic pathway and which catalyzes the dephosphorylation of 1,3-bisphosphoglycerate to produce ATP, has been observed in many malignant tumor tissues that are dependent on ATP as a major energy source." (PMID 17187689, 2006). "On the contrary, increased protein and mRNA levels of LDHA, PGK1, and HK1 were detected in cancer cells cultured at different concentrations of NaLac." (PMID 40849487, 2025). "By analyzing the CCLE (Cancer Cell Line Encyclopedia) database, we identified N87 and MKN7 as cell lines with high expression of HER2 and PGK1." (PMID 40786054, 2025). "miR‐5586‐5p also suppresses the expression of glycolytic genes, lactate dehydrogenase A (LDHA), hexokinase 2 (HK2), phosphoglycerate kinase 1 (PGK1), and solute carrier family 2 member 1 (SLC2A1), thereby suppressing glycolysis and cancer progression." (PMID 40448344, 2025). "PGK1 and PKM2 are the only two enzymes that control ATP production during aerobic glycolysis in cancer cells." (PMID 39594816, 2024). "In general, PGK1 activates the CXCR4/ERK pathway and accelerates glycolysis to enhance cancer progression and sorafenib resistance in KIRC cells." (PMID 35121728, 2022).
cancer (continued). "Humans have two PGK isoenzymes, PGK1 and PGK2, with the former being overexpressed in various cancers and modulated through a variety of mechanisms." (PMID 36276846, 2022). "The corresponding heatmap analysis also indicated a positive correlation between P4HA1 and these five genes (BNIP3L, FUT11, LDHA, PGK1, and RPL17P50) in the majority of 32 types of cancers." (PMID 35812752, 2022). "The expression of SLC6A8 exhibited the strongest positive correlation with that of ADM, GPI, NDRG1, PGK1, and PNCK, and their correlation with SLC6A8 expression in distinct cancer types were illustrated by the heatmap, respectively." (PMID 36061183, 2022). "A significant number of studies have shown that genes participating in both glucose and glutamine transport and metabolism, including PGK1, PFK1, and so on, exert tremendous influences on the metabolic adaptation, proliferation, and metastasis of cancer cells." (PMID 36358653, 2022). "From the results presented in this study, we propose a novel model in which the PGK1 binds to HTATSF1 and exerts functional control of cancer metastasis." (PMID 34091600, 2021). "The highest glycolysis score, PGK1 and PGAM1 mRNA abundance were observed under high hypoxia and high HSPA8 expression across cancer types." (PMID 32635458, 2020). "The highest glycolysis score, LDHA and PGK1 mRNA abundance were observed under high hypoxia and high P4HA1 expression in some cancer types." (PMID 32635458, 2020). "Phosphoglycerate kinase 1 (PGK1) is the first adenosine triphosphate (ATP)-generating glycolytic enzyme in the aerobic glycolysis pathway and plays an important role in cancer development and progression." (PMID 33344462, 2020). "PGK1 and G6PD, as crucial metabolic markers of glycolysis and the pentose phosphate pathway, have been demonstrated to favor metastasis of various cancers." (PMID 32028979, 2020). "Depletion of PGK1 in the normal colon cell CRYPT also inhibited cell proliferation, but to a less extent compared to the cancer cell lines." (PMID 31911580, 2020). "Attenuating the enzymatic activity of PGK1 by targeting its post-translational modifications (including phosphorylation, acetylation, ubiquitination, etc.)which have been shown significantly altered in cancer might reduce systemic toxicity and is an alternative approach." (PMID 32070368, 2020). "The elevated expression, promoter hypomethylation, and phosphorylation of PGK1 and PDHK1 were related with disease progression and short OS in diverse types of cancer." (PMID 31578148, 2019). "We also analyzed the clinical relevance of PGK1 S203 and PDHK1 T338 phosphorylation levels by conducting immunohistochemical experiments in an additional 818 independent cancer cases (including 619 with paired normal tissues)." (PMID 31578148, 2019). "Using specific antibodies against PGK1 S203 and PDHK1 T338 phosphorylation, we performed immunohistochemistry with tissue microarray assay in additional 818 cancer cases with 619 paired normal tissues from five cancer types." (PMID 31578148, 2019). "We aimed to evaluate the pathological progression value and prognostic values of PGK1 mRNA high expression, PGK1 promoter methylation, and PGK1 mediated-PDHK1 activating phosphorylation in multiple human cancers." (PMID 31578148, 2019). "In the present study, we identified relationships of high PGK1 mRNA level and promoter hypomethylation with advanced TNM stage and short OS in multiple cancer types in a pan-cancer analysis of TCGA data involving 11,908 cases covering 34 cancer types." (PMID 31578148, 2019). "Experimental and clinical studies have demonstrated the pivotal role of PGK1 and G6PD in cell malignance and cancer metastasis." (PMID 29954422, 2018). "A recent study highlighted that PGK1 acted as a protein kinase in coordinating glycolysis and the TCA, which is instrumental in cancer metabolism and tumourigenesis." (PMID 28112229, 2017).
cancer (continued). "Using normal and cancer tissue from CRC patients we examined the stability of the nine candidate reference genes, finding PGK1, GUSB and PP1A to be the most stably expressed." (PMID 26962435, 2016). "A close relationship between phosphoglycerate kinase 1 (PGK1) and the CXCR4/SDF1 axis (chemokine receptor 4/stromal cell derived factor 1) has been shown for several cancers." (PMID 24376734, 2013). "Notably, genes like fatty acid binding protein 5 (FABP5), enolase 1 (ENO1), phosphoglycerate kinase 1 (PGK1), and marker of proliferation Ki-67 (MKI67), which have been extensively studied in cancer biology, were included." (PMID 41328179, 2026). "Comparison of positive expression of PGK1 in cancer tissues between recurrence group and non-recurrence group [n (%)]." (PMID 40771921, 2025). "For instance, in Glycolysis/ Gluconeogenesis and Biosynthesis of amino acids pathways, lysine 131 (K131) site of PGK1, K322 and K13 sites of ALDOA, K215 and K194 sites of GAPDH, K89 site of ENO1, K678 site of PFKM were hyper-lactylated in cancer cells and tissues." (PMID 40849487, 2025). "We also identified the top 1 GEAR in individual cancer types, such as TLL1 (BLCA), PGK1 (BRCA), RFXANK (CESC), DPP7 (COAD), VWA8 (KIRC), SCMH1 (LGG), HILPDA (LIHC), TLE1 (LUAD), CD151 (LUSC), ANKRD13A (OV), SOCS2 (PAAD), DRG2 (PRAD), ADAMTS6 (STAD), PSMB8 (THCA), ASS1 (UCEC)." (PMID 41404730, 2025). "The PGK1 high expression rate in the cancer tissues of the recurrence group was higher than that of the cancer tissues of the non-recurrence group (P < 0.05)." (PMID 40771921, 2025). "Key enzymes in glycolysis such as glucose transporter 1 (GLUT1), hexokinase 2 (HK2), phosphoglycerate kinase 1 (PGK1), pyruvate kinase M2 (PKM2), lactate dehydrogenase A (LDHA), and monocarboxylate transporter 4 (MCT4) have been observed to be highly expressed in cancer tissues." (PMID 39594816, 2024). "Moreover, PGK1 is a transcriptional target of HIF-1α and enhances HIF-1α activity, forming a feedback loop that promotes cancer metastasis." (PMID 39590296, 2024). "However, PGK1 phosphorylates PRAS40, inhibits autophagy-mediated cell death and promotes tumorigenesis in early-stage or cancer cells with sufficient oxygen or nutrient supply." (PMID 37723547, 2023). "HKs (HK1 and HK2), PFK1 and PFK2, G6PD, pyruvate kinase, phosphoglycerate dehydrogenase (PHGDH), lactate dehydrogenase, phosphoglycerate kinase 1 (PGK1), enolase (ENO), isocitrate dehydrogenase (IDH), and glucose transferase (GLUT) serve as ideal pharmacological targets to treat cancer." (PMID 36984785, 2023). "Five enzymes involved in glycolysis present only or mainly in sEVs isolated from cancer-derived cell lines were validated: aldolase (ALDOA), glyceraldehyde-3-phosphate dehydrogenase (GAPDH), phosphoglycerate kinase (PGK1), enolase (ENO) and pyruvate kinase (PKM)." (PMID 37189694, 2023). "Given the critical role of PGK1 in the initiation and progression of tumorigenesis, it is not surprising that PGK1 dysregulation frequently occurs in human cancer tissues." (PMID 37723547, 2023). "The glycolytic enzyme PGK1 is involved in the HIF1α transcription factor network, in which PGK1 together with pyruvate kinase M2 (PKM2) controls the ATP production during aerobic glycolysis in cancer cells (also known as the “Warburg effect”)." (PMID 36038612, 2022). "On the other hand, co‐culture with TANs led to increase of SPI1 expression and its enrichment on HK2 or PGK1 promoter in LoVo and HCT116 cells, resulting in increase of HK2 or PGK1 promoter activity and transcript levels, while silencing of SPI1 in cancer cells reduced these effects." (PMID 34841706, 2021). "Phosphoglycerate kinase 1 (PGK1) is a crucial ATP-producing enzyme in the glycolytic pathway, which is regulated by the hypoxia-inducible transcriptional factor (HIF-1) and plays a role in cancer progression and development." (PMID 34768930, 2021).
cancer (continued). "PGK1 can also act as a protein kinase to phosphorylate pyruvate dehydrogenase kinase 1 (PDHK1), whose regulation coordinates glycolysis and the tricarboxylic acid (TCA) cycle in cancer metabolism and tumorigenesis." (PMID 34445528, 2021). "We also investigated the influence of PGK1 expression on OS, PFI, DSS, and DFI across pan-cancer." (PMID 34790279, 2021). "Persistent and sustained ERK1/2 activation, induced by mutant BRAF or KRAS, leads to mitochondrial translocation of phosphoglycerate kinase 1 (PGK1) and phosphorylation of PDK1, which in turn inactivates PDH, contributing to aerobic glycolytic switch in cancer." (PMID 32528879, 2020). "In addition, a recent study demonstrated the role of mitochondrial PGK1 in coordinating glycolysis and the TCA cycle in cancer cells." (PMID 32276500, 2020). "Phosphoglycerate kinase 1 (PGK1), an essential enzyme in aerobic glycolysis elevated in tumors and serum from cancer patients, has not been previously found in bile." (PMID 32575903, 2020). "Here, we performed a pan-cancer analysis of clinical relevance of PGK1 using data from 11,908 cases (including 1582 with paired normal tissues) across 34 cancer types from The Cancer Genome Atlas (TCGA) datasets." (PMID 31578148, 2019). "In addition, the 15 cancer types account for 55.0% of cancer incidence and 63.1% of cancer mortality each year worldwide (data from GLOBOCAN 2018), indicating that PGK1 overexpression is prevalent among the most deadly human cancers." (PMID 31578148, 2019). "We also detected mitochondrial PGK1-dependent PDHK1 T338 phosphorylation in additional cases of five cancer types and demonstrated that mitochondrial function of PGK1 significantly affected the clinical behaviors of patients with these cancers." (PMID 31578148, 2019). "Phosphoglycerate kinase 1 (PGK1) is a glycolytic enzyme that catalyzes the transfer of the phosphate from the 1 position of 1,3-diphosphoglycerate to ADP, generating 3-phosphoglycerate and ATP, and has been shown to be overexpressed in multiple cancer types." (PMID 31877888, 2019). "Alteration of PGK1 levels has been reported in different cancer types and this enzyme is considered as a negative prognostic marker." (PMID 29995887, 2018). "Normalization with PGK1 and GPX1 might have diluted the tumorous heterogeneities among cancer patients." (PMID 29915691, 2018). "A close relationship between PGK1 and the CXCR4/SDF1 axis is known for several cancers." (PMID 24376734, 2013). "Therefore suppressing PGK1/PRAS40 signaling could be possible to induce autophagy-mediated cell death under normoxia, which is anticipated to offer novel insights to target cancer." (PMID 35058442, 2022). "Our findings identified a novel regulatory mechanism of GSK3β expression involving metabolic enzyme PGK1-coupled Hsp90, and highlighted the potential for more effective cancer treatment by selecting Hsp90 inhibitors that do not affect PGK1-regulated GSK3β expression." (PMID 34403222, 2021). "However, all these studies focused on the metabolic function of PGK1 without elucidating the relationship between cancer progression and gene modification and the mitochondrial function of PGK1." (PMID 31578148, 2019). "Recently, phosphoglycerate kinase 1 (PGK1), an ubiquitous enzyme expressed in all somatic cells that catalyzes the seventh step of glycolysis which consists of the reversible phosphotransfer reaction from 1,3-bisphosphoglycerate to ADP, has been discovered to be overexpressed in many cancer types." (PMID 29995887, 2018). "However, both HIF-1α and PGK1 were found to be down-regulated in CSC-like cancer cells compared to non-CSC cancer cells." (PMID 24423398, 2013). "However, the effects of these PGK1 inhibitors on cancer cells have not been reported." (PMID 37723547, 2023).